HMGCS2 (3-hydroxy-3-methylglutaryl-CoA synthase 2)
Diseases named in the same sentence as HMGCS2 in open-access papers (continued):
Sharing a sentence is not in itself a finding about the gene and the disease.
Sepsis (5 papers, 2020 to 2025). Sepsis is defined as life-threatening organ dysfunction caused by a dysregulated host response to infection. "The inhibition of Hmgcs2 exacerbated the inflammatory response and decreased M2 macrophages in the heart, that is Hmgcs2 can regulate M2 polarization of macrophages to repair myocardial injury induced by sepsis." (PMID 37561521, 2023). "As a consequence of the PPARα decline, some PPARα‐responsive genes such as Hmgcs2 follow the gradual decline in mRNA levels in liver after sepsis." (PMID 31916705, 2020). "The wide gap and severe metabolic acidosis could be attributed to sepsis, poor tissue perfusion, and defective HMGCS2 enzymes." (PMID 40548098, 2025). "Moreover, it was found that live L. murinus could markedly elevate serum levels of metabolite 3-HB and alleviate sepsis-related injury, while the knockout of the key enzyme for 3-HB synthesis Hmgcs2 in the liver negated this protective effect." (PMID 40223164, 2025). "We conducted a public data mining analysis of the transcriptome results of CLP mice to explore the regulatory mechanism of sepsis-induced myocardial injury, discovering that Hmgcs2 was highly expressed in the cardiac tissues of the mice and could be a crucial factor in the condition." (PMID 37561521, 2023). "The cecal ligament and puncture (CLP) model was used to induce sepsis in C57BL/6 mice, with Hmgcs2 expression in the myocardium of the mice being heightened and inflammatory factors being augmented." (PMID 37561521, 2023). "Our research revealed that Hmgcs2 inhibited the activation of pro-inflammatory macrophages and, through Src-dependent activation of PI3K/Akt pathway, promoted the anti-inflammatory phenotype, thus safeguarding myocardial damage from sepsis." (PMID 37561521, 2023).
type 1 diabetes (5 papers, 2017 to 2025). "Inhibition of HMGCS2 may therefore represent a novel cardioprotective strategy, perhaps of particular relevance to the diabetic heart, where sensitivity to ischaemia/reperfusion injury and, at least in the case of type 1 diabetes, expression of HMGCS2 are both increased." (PMID 34491199, 2021).
type 2 diabetes (5 papers, 2013 to 2023). "In addition, overexpression of the Hmgcs2 and an increase in HMGCS2 levels in the kidney under some conditions, such as starvation or diabetes type 2, indicate the potential for ketogenesis to occur in the kidney." (PMID 36768899, 2023). "Recently, it was shown that the expression of HMGCS2 was increased fourfold in diabetic kidneys, which leads to increased renal ketogenesis and plays an important role in the pathogenesis of diabetic nephropathy in type 2 diabetes." (PMID 23308176, 2013). "We checked the expression of HMGCS2 reflecting ketone body synthase, SMCT1 reflecting ketone body reabsorption, and SCOT reflecting the utilization of ketone bodies in high-fat diet-induced type 2 diabetes." (PMID 36237185, 2022).
cardiac hypertrophy (4 papers, 2021 to 2025). "We suggested that DAPA mediated the Plin5/PPARα signal axis, and ultimately affected the expression level of PDK4 and HMGCS2, myocardial cell metabolism, and relieve the pathological progression of cardiac hypertrophy." (PMID 34630108, 2021). "Considering that Nppa, Nppb and Myh7 are not only embryonic marker genes but also markers of cardiac hypertrophy, we infer that Hmgcs2 knockout causes cardiac stress, but does not affect cardiac development." (PMID 36220812, 2022). "We demonstrated that DAPA could activate the Plin5/PPARα signaling pathway and further significantly promoted the expressions PDK4 and HMGCS2 in cardiac hypertrophy." (PMID 34630108, 2021).
colitis (4 papers, 2021 to 2025). Inflammation of the colon. "3-Hydroxy-3-methylglutaryl-CoA synthase 2 (HMGCS2), the key enzyme in ketogenesis, is highly expressed in the colonic epithelium, and its activity has been directly linked to protection against experimental colitis." (PMID 41222705, 2025). "The activation of PPAR-α, PPAR-δ, and Scd1 has been shown to play a role in DSS-colitis, and Hmgcs2 has an effect in TNBS-colitis." (PMID 34504431, 2021). "Western blotting revealed reduced expression of HMGCS2, ARG1, and CD206 and increased expression of iNOS and CD86 in colon tissues from the mouse models of DSS-induced colitis, further validating these findings." (PMID 38633005, 2023). "Expression of HMGCS2 and macrophage polarization markers was verified in DSS-induced colitis mice model." (PMID 38633005, 2023). "To investigate if the UPR could directly induce HMGCS2 downregulation in vivo, we injected tunicamycin in C57BL/6 wild type mice as well as in Xbp1ΔIEC mice, which display a defective UPR through the deletion of Xbp1 in IECs resulting in an ER associated spontaneous enteritis, but not colitis." (PMID 37457727, 2023).
diabetic nephropathy (4 papers, 2013 to 2025). "This study was designed to elucidate the contribution of Hmgcs2 in the pathogenesis of obese diabetic kidney disease mice." (PMID 40708536, 2025). "Although recent studies have indicated that HMGCS2 is involved in diabetic nephropathy, whether HMGCS2 is expressed in the PRAT and its related biological functions remain unclear." (PMID 40708536, 2025).
non-alcoholic fatty liver disease (4 papers, 2020 to 2023). "Our study also found that the increased expression of HMGCS2 in the HFD-fed mice is associated with Wnt3a/β-catenin abundance in nonalcoholic fatty liver disease." (PMID 33647884, 2021). "Mice lacking HMGCS2 expression caused insufficient ketogenesis under high-fat diet feeding, which promoted the development of nonalcoholic fatty liver diseases." (PMID 32635582, 2020). "Mice lacking Hmgcs2 exhibited ketogenic deficiency and develop non-alcoholic fatty liver disease spontaneously." (PMID 37047689, 2023). "They found that the high-fat-diet feeding of HMGCS2-eliminated mice resulted in increased hepatic injury and inflammation and, therefore, suggested that ketogenesis may modulate nonalcoholic fatty liver disease." (PMID 32635582, 2020).
oral cancer (4 papers, 2017 to 2024). "In contrast, previous research showed that HMGCS2 enhances invasion and metastasis by directly interacting with PPARα to activate Src signaling in colorectal and oral cancers." (PMID 38923428, 2024). "HMGCS2 may promote the metastasis of CRC and oral cancer cells in a ketogenesis enzymatic-independent manner via HMGCS2/PPARα/Src axis activation." (PMID 32155177, 2020). "These investigators suggested that HMGCS2 may be a therapeutic target in colorectal or oral cancer." (PMID 34298684, 2021).
pulmonary fibrosis (4 papers, 2024 to 2025). Chronic progressive interstitial lung disorder characterized by the replacement of the lung tissue by connective tissue, leading to progressive dyspnea, respiratory failure, or right heart failure. "The results indicated that a specific deficiency of HMGCS2 in AECIIs was vital for lung fibrosis progression." (PMID 38658970, 2024). "Interestingly, by analyzing the GEO data set (GDS1492), we found that the C57BL/6 mice strain (a widely used mice strain for establishing Bleomycin lung fibrosis), which was more susceptible to Bleomycin injury, showed lower HMGCS2 expression." (PMID 38658970, 2024). "Interestingly, by analyzing the GEO data set, we found that the C57BL/6 mice strain that was more susceptible to Bleomycin-induced pulmonary fibrosis showed lower HMGCS2 expression." (PMID 38658970, 2024). "The decreased expression pattern of HMGCS2 was further confirmed in the Bleomycin-induced mice lung fibrosis model." (PMID 38658970, 2024). "Taken together, these data indicated that HMGCS2 could mitigate Bleomycin-induced lung fibrosis by decreasing lipid accumulation in AECIIs." (PMID 38658970, 2024). "Furthermore, oil-red staining showed that HMGCS2 overexpression decreased lipid accumulation upon Bleomycin injury, which further confirmed that HMGCS2 ameliorated lung fibrosis by facilitating lipid metabolism in AECIIs." (PMID 38658970, 2024). "3-hydroxy-3-methylglutaryl-CoA synthase 2 (HMGCS2) is involved in the regulation of lipid metabolism of AEC2 cells at the onset and progression of pulmonary fibrosis, making it another target for clinical interventions." (PMID 40559469, 2025). "In conclusion, these data suggested that HMGCS2 facilitated lipid metabolic of AECIIs through interacting with PPARα to promote the expression of CPT1A and CPT2 in mice lung fibrosis models." (PMID 38658970, 2024). "A mitochondrial-located lipid metabolic gene 3-hydroxy-3-methylglutaryl-Coa Synthase 2 (HMGCS2) was significantly decreased in all the data sets and the protein level of HMGCS2 was further confirmed using IHC in IPF lung sections and mice lung fibrosis model." (PMID 38658970, 2024). "In conclusion, these data suggested that HMGCS2 facilitated lipid metabolism of AECIIs through interacting with PPARα, which promoted the expression of CPT1A and CPT2 in mice lung fibrosis models." (PMID 38658970, 2024). "Therefore, we assumed that HMGCS2 might act as a transcriptional coactivator of PPARα in regulating the expression of PPARα target genes such as CPT1A and CPT2 in lung fibrosis." (PMID 38658970, 2024). "Furthermore, HMGCS2 could increase the expression of CPT1A and CPT2 in lung fibrosis models in mice." (PMID 38658970, 2024). "Furthermore, HMGCS2 could increase the expression of CPT1A and CPT2 in mice with lung fibrosis." (PMID 38658970, 2024).
rectal cancer (4 papers, 2019 to 2022). A primary or metastatic malignant neoplasm that affects the rectum. "High expression of HMGCS2 caused poor susceptibility of rectal cancer to chemoradiotherapy." (PMID 31779269, 2019). "However, in rectal cancer, high expression of HMGCS2 predicted poor disease-free survival, local recurrence-free survival, and metastasis-free survival." (PMID 31886185, 2019).
ulcerative colitis (4 papers, 2022 to 2025). An inflammatory bowel disease involving the mucosal surface of the large intestine and rectum. "Reduced HMGCS2 expression in ulcerative colitis patients may exacerbate intestinal inflammation." (PMID 40298760, 2025). "Key differentially expressed genes in the array also exhibited transcriptional alterations in colonic biopsies from active Ulcerative Colitis patients, including NKG2D ligands and the enzyme HMGCS2." (PMID 37457727, 2023).
Encephalopathy (3 papers, 2020 to 2025). Encephalopathy is a term that means brain disease, damage, or malfunction. "A 2‐year‐old boy with a novel HMGCS2 variant presented with refractory seizures and encephalopathy, highlighting the need for rapid metabolic and genetic evaluation for timely management." (PMID 41383544, 2025).
HMGCS2) deficiency (3 papers, 2019 to 2024). "Pathogenic mutations on the HMGCS2 gene cause mitochondrial HMG-CoA synthase deficiency which disrupts the ketogenesis and blocks the energy supply to the brain during the fasting state." (PMID 35308163, 2021).
Hyperglycemia (3 papers, 2020 to 2025). An increased concentration of glucose in the blood. "Furthermore, HMGCS2-deficient mice display hyperglycemia and impaired gluconeogenesis." (PMID 37670031, 2023). "Knockdown of HMGCS2 can alleviate the hyperglycemia-induced mitochondrial division of glomerular endothelial cells." (PMID 40361044, 2025). "Similarly, Knockdown of HMGCS2 can alleviate the hyperglycemia-induced mitochondrial fission and mitochondrial dysfunction of glomerular endothelial cells." (PMID 40361044, 2025). "In terms of lipid oxidative genes, including HMGCS2, CPT2 and CPT1A, no significant changes were observed, indicating that lipid oxidation might not be responsible for the increased lipid deposition in liver, at least not in the early stages of hyperglycaemia or hyperlipidemia induced NAFLD." (PMID 33186123, 2020).
hyperlipidemia (3 papers, 2020 to 2023). "After cessation of PM exposure, hyperlipidemia downregulated Fas gene expression and upregulated Hmgcs2 expression with negative feedback decreasing the hyperlipidemia to the normal level." (PMID 36984803, 2023).
Insulin resistance (3 papers, 2015 to 2024). Increased resistance towards insulin, that is, diminished effectiveness of insulin in reducing blood glucose levels. "As insulin suppresses Hmgcs2 expression in hepatocytes, it is reasonable to postulate that higher insulin levels inhibit ketogenesis in the presence of hepatic insulin resistance." (PMID 35421611, 2022). "Thus, in mIR/HFD mice, unsuppressed lipolysis in adipocytes as we previously reported, and enhanced hepatic Hmgcs2 expression due to hepatic insulin resistance may potentiate BHB production and result in renal gluconeogenic gene transactivation." (PMID 38604598, 2024).
kidney damage (3 papers, 2013 to 2026). "Hmgcs2, Cyp4a10, Cyp4a14 and Lpl were identified as the major proteins/genes associated with DQ-induced kidney damage." (PMID 36851058, 2023). "Overall, the multi-omics analysis showed that DQ-induced kidney damage is associated with dysregulation of the PPAR signaling pathway, and an aberrant increase in Hmgcs2 expression and 3-hydroxybutyric acid levels." (PMID 36851058, 2023). "In our data, the presence of HMGCS2 in kidney of A/J mice might turn these animals more prone to nephropathy, which could impair F reabsorption in kidneys." (PMID 23308176, 2013).
liver disease (3 papers, 2010 to 2025). "In summary, the HMGCS2-mediated regulation of ketogenesis represented an important mechanism underlying the attenuation of liver disease progression in NASH-T2DM comorbidity." (PMID 40867627, 2025). "Immunohistochemical staining of human liver disease tissue arrays showed that HMGCS2 is abundantly expressed in normal liver tissues but is downregulated in cirrhosis and HCC tissues." (PMID 31779269, 2019). "In conclusion, the present study demonstrated that cynaroside promoted ketone body production in the liver through the up-regulation of HMGCS2, which in turn inhibited hepatocyte senescence in order to ameliorate NASH-combined T2DM and slow down the progression of liver disease." (PMID 40867627, 2025).
melanoma (3 papers, 2016 to 2023). A malignant, usually aggressive tumor composed of atypical, neoplastic melanocytes. "The effect of HMGCS2 on cell proliferation was supported by previous research showing that fenofibrate-induced HMGCS2 upregulation in melanoma cells was accompanied by proliferation arrest." (PMID 31779269, 2019). "This suggests that in the melanoma cells we studied, either PPARa does not play a role as an HMGCS2 transactivator or that the process might also be regulated downstream of transcription – perhaps through altered protein stability or turnover rate." (PMID 26869992, 2016).
acute pancreatitis (2 papers, 2023). An acute inflammatory process that leads to necrosis of the pancreatic parenchyma. "Coincidentally, HMGCS2 knockdown exacerbates the macrophage-activated inflammatory response in acute pancreatitis." (PMID 38633005, 2023). "Hmgcs2 ketogenesis acts as an endogenous protective program during acute pancreatitis by suppressing inflammatory macrophage activation." (PMID 37561521, 2023).
colorectal adenocarcinoma (2 papers, 2019). The most common type of colorectal carcinoma. "In colorectal adenocarcinoma, HMGCS2 expression was downregulated in moderately and poorly differentiated carcinomas, which implied the role of HMGCS2 in the regulation of tumor differentiation." (PMID 31779269, 2019). "Indeed, our laboratory and others have found that low expressions of HMGCS2 protein were observed in moderately and poorly differentiated colorectal adenocarcinomas compared with well-differentiated tumors." (PMID 31546785, 2019).
colorectal tumors (2 papers, 2022 to 2023). "Studies have found that HMGCS2 is significantly up-regulated in the intestinal mucosa of long-term UC patients, but down-regulated in most colorectal tumors." (PMID 36419192, 2022). "Compared to that in UC tissues, significantly less HMGCS2 was expressed in colorectal tumors." (PMID 38633005, 2023).
liver fibrosis (2 papers, 2022 to 2023). "It has been reported that the inhibition of HMGCS2 in the liver will cause the impairment of hepatic ketogenesis, which can promote liver fibrosis through the various factors derived from the injured hepatocytes and activation of macrophages." (PMID 36629048, 2023). "As hepatic fibrosis is the major determinant of liver decompensation in NAFLD patients, we tested whether HMGCS2-OE could improve liver fibrosis." (PMID 35421611, 2022). "Collectively, these results suggest that increased ketogenesis by HMGCS2-OE effectively improves the HFD-induced hepatosteatosis and associated abnormal glucose metabolism in mice, however, may not reverse liver fibrosis." (PMID 35421611, 2022). "However, picrosirius red (PSR) staining and formal histological scoring for liver fibrosis, as well as the measurement of liver collagen levels indicated no improvement of hepatic fibrosis with HMGCS2-OE." (PMID 35421611, 2022). "While we conclude that HMGCS2-OE does not have a statistically significant effect on liver fibrosis and inflammation in NAFLD, there was, however a trend towards increased hepatic fibrosis and liver injury markers in Ad-HMGCS2 mice." (PMID 35421611, 2022).
lymph node metastasis (2 papers, 2017 to 2023). "Furthermore, lymph node metastasis (N) was associated with HMGCS2 expression in BRCA, STES, KIPAN, STAD, HNSC, KIRC, and THCA (P < 0.05)." (PMID 37670031, 2023). "In CRC, higher HMGCS2 mRNA expression levels were significantly associated with advanced TNM staging (P = 0.009) and lymph node metastasis (P < 0.001)." (PMID 27816970, 2017).
metastasis (2 papers, 2017 to 2023). The spread or migration of cancer cells from one part of the body (where they first appeared) to another. "To assess the clinical relevance of HMGCS2 expression, we investigated its relationship with overall survival (OS), primary tumor status (T), lymph node metastasis (N), distant metastasis (M), tumor grade (G), and tumor stage." (PMID 37670031, 2023).
renal fibrosis (2 papers, 2023 to 2025). A final common manifestation of a wide variety of chronic kidney diseases characterized by glomerulosclerosis and tubulointerstitial fibrosis. "Overall, our results suggest that LONP1, to the best of our knowledge, acts as an important factor in the renal fibrosis of CKD by degrading HMGCS2 and thereby regulating mitochondrial homeostasis." (PMID 36629048, 2023). "Collectively, these results demonstrate that LONP1 attenuated mitochondrial dysfunction and renal fibrosis, possibly by degrading HMGCS2 to prevent the accumulation of HMGCS2 under CKD conditions." (PMID 36629048, 2023). "Here, we found Lonp1 deletion impaired mitochondrial homeostasis and aggravated renal fibrosis through HMGCS2 accumulation in CKD mice or cellular models, whereas Lonp1 overexpression or treatment with an LONP1 activator alleviated these injuries." (PMID 36629048, 2023). "Next, to investigate the role of HMGCS2 in terms of mitochondrial function and renal fibrosis, we firstly performed IHC staining with biopsied kidney tissues from CKD patients." (PMID 36629048, 2023). "In our study, HMGCS2 promoted renal fibrosis by damaging mitochondrial function." (PMID 36629048, 2023). "However, the exact role of HMGCS2 in renal fibrosis remains unclear." (PMID 36629048, 2023). "Thus, pemafibrate inhibits EMT via HMGCS2‐mediated production of BHB, thereby attenuating renal fibrosis by protecting the kidneys." (PMID 39887648, 2025). "However, no direct evidence has indicated that HMGCS2 is involved in renal fibrosis." (PMID 36629048, 2023).
viral infection (2 papers, 2023 to 2024). "Interestingly in close parallels to our study emphasizing relationship between the mevalonate pathway and viral infection, previous reports have shown that suppressing HMGCS2 or ACAA2 expression may suppress papillomavirus or poxvirus infection 25,26." (PMID 37369697, 2023).